MIAT (myocardial infarction associated transcript)
Diseases named in the same sentence as MIAT in open-access papers (continued):
Sharing a sentence is not in itself a finding about the gene and the disease.
cancer (54 papers, 2016 to 2026). A tumor composed of atypical neoplastic, often pleomorphic cells that invade other tissues. "Further studies are needed to elucidate the precise role of MIAT rs1061540 in cancer and its potential as a biomarker for cancer risk assessment." (PMID 38390896, 2024). "Some of the irlncRNAs previously associated with the malignant phenotypes of various cancers, including MIAT, TYMSOS, LINC01063, HOXC-AS1, LINC02454, SCAT1, and LINC01322 were identified in the process of modeling in this study." (PMID 34167440, 2021). "Besides, dysregulation of MIAT has been associated with abnormal activity of numerous cancer-related signaling pathways such as B cell receptor, JAK-STAT, MAPK, and TNFA-NFKB signaling, indicating its role in the regulation of these signaling pathways." (PMID 34771679, 2021). "Finally, pathway enrichment analyses implied that lncRNA MIR205HG and MIAT were associated with multiple cancer-related pathways, especially epidermis development and immune response." (PMID 31649871, 2019). "Recent studies have also implicated MIAT in cancer initiation and progression." (PMID 29914974, 2018). "The long non-coding RNA myocardial infarction associated transcript (MIAT) has been implicated in the development and progression of several cancers." (PMID 41938500, 2026). "MIAT is also overexpressed in breast cancer cell lines and biopsies, promoting cancer progression, whereas it is secreted in exosomes in the context of gastric cancer." (PMID 40429961, 2025). "The level of MIAT is found to be upregulated in paclitaxel-resistant cancer cells both in clinical serum and cell lines underwent paclitaxel administration." (PMID 40781643, 2025). "Due to mounting evidence showing the pivotal role of MIAT throughout cancer processes, the current study aims to elucidate the functions of lncRNA MIAT in T and chronic myeloid leukemic cells." (PMID 37624039, 2023). "This investigation also aims to investigate the effects of MIAT silencing on the expression of core genes involved in cancer." (PMID 37624039, 2023). "Nevertheless, little is known regarding the effects of MIAT dysregulation and how the modulation of its expression is potentially relevant to cancer progression and prognosis." (PMID 37624039, 2023). "For instance, MIAT is highly expressed in lung cancer and neuroendocrine prostate cancer and interacts with multiple genes to participate in cancer development, which has been widely perceived as a therapeutic target." (PMID 37025425, 2023). "Upregulated MIAT exerts its carcinogenic effect by inhibiting downstream cancer suppressor DLG3, whereas silencing MIAT inhibits cell viability, migration and invasion, and EMT." (PMID 37901333, 2023). "Increasing evidence connected the dysregulation of the expression of MIAT with carcinogenesis and the progression of various cancer types, highlighting the pivotal oncogenic or the tumor-suppressive role of this lncRNA." (PMID 37624039, 2023). "MIAT can act as ceRNA to regulate a variety of signal pathways in the cytoplasm and participate in the regulation of cancer cell proliferation, cycle, migration, invasion, and drug resistance." (PMID 36230580, 2022). "The evidence from the literature revealed that lncRNA MIAT plays a crucial role in cellular proliferation, migration, and invasion in various cancers." (PMID 35607443, 2022). "A query to the lnc2Cancer database showed that eight of the 14 differential hub lncRNAs (LINC00909, BZRAP1-AS1, C17orf76-AS1, HCG11, MIAT, SNHG5, SNHG15, and TP73-AS1) were associated with various types of carcinomas in previous studies." (PMID 35432537, 2022). "MIAT in human cancers can act as a competitive endogenous RNA, play the role of miRNA sponge, regulate some signaling pathways, and affect some epigenetic modulators such as histone deacetylases and DNA methyltransferases." (PMID 33806217, 2021).
cancer (continued). "Despite that the MIAT role in the development of several human cancers has been acknowledged, its specific molecular mechanisms remain to be fully elucidated." (PMID 34771679, 2021). "The MIAT-related research was predominantly focused on cancer, in which MIAT was validated as a promoter of tumor development." (PMID 34124371, 2021). "In particular, we found that the cancer-related lncRNAs PVT1 and MIAT were significantly correlated with CD8 T-cell infiltration in several cancer types." (PMID 32081859, 2020). "Reduced MIAT expression dramatically attenuated cancer cell proliferation, inhibited epithelial‐mesenchymal transition (EMT) and stimulated apoptosis." (PMID 32274858, 2020). "Consistent with the results obtained from clinical samples, MIAT transcripts were down-regulated in cancer cell lines compared to H8 cells." (PMID 32549789, 2020). "Recent studies have reported that MIAT is upregulated in several types of cancers including papillary thyroid, lung and colorectal cancer." (PMID 33154765, 2020). "When MIAT is downregulated, cancer cell proliferation is repressed, cellular apoptosis is induced, and cell senescence occurs, making MIAT a contender as a possible therapeutic target, as well as a diagnostic tool." (PMID 32466143, 2020). "Later, overexpression of MIAT was discovered in several types of cancers including neuroendocrine prostate cancer, breast cancer and chronic lymphocytic leukemias." (PMID 31372094, 2019). "The following studies found that lncRNA MIAT was involved in various diseases, such as MI, diabetic retinopathy, paranoid schizophrenia, microvascular dysfunction and cancer." (PMID 29487526, 2018). "Evidence implicating MIAT in cancer is now emerging and MIAT is selectively up-regulated in neuroendocrine prostate cancer and in primary leukemic cells from patients with aggressive forms of CLL." (PMID 29914974, 2018). "The mechanism for MIAT to exert chemoresistance to cancer cells is that MIAT can recruit a transcription factor, TATA-box binding protein-associated Factor 1 (TAF1), in the promoter region of sterol regulatory element binding transcription factor 1 (SREBF1) and enhance the expression of SREBF1." (PMID 40781643, 2025). "Additionally, exosomal MIAT is also shown to be secreted from the cancer cells and transferred into other cancer cells to spread the chemoresistance to paclitaxel." (PMID 40781643, 2025). "Although the currently studied variant rs1061540 has not been previously associated with cancer, other MIAT-related SNPs have been associated with cancer risk." (PMID 38390896, 2024). "In addition, gene expression analysis showed the expression of a variety of core cancer genes as being affected by the silencing of MIAT, highlighting the crucial role of MIAT in carcinogenesis and cancer progression." (PMID 37624039, 2023). "All of these results indicate that MIAT is a cancer-promoting gene." (PMID 34811354, 2021). "MIAT has also been widely reported to play a tumor‐promoting role in many other cancer types." (PMID 32274858, 2020). "In this study, by integrating the expression profiles of the GEO datasets GSE45827 and GSE65216, we identified hundreds of differentially expressed lncRNAs, including HOTAIR, ASAP1-IT1, TUG1, and MIAT, which have been reported to be related to cancer by other investigators." (PMID 32352014, 2020). "Our data showed that miR-324-3p was directly targeted by MIAT, suggested that MIAT might promote cancer progression via miR-324-3p." (PMID 31372094, 2019). "The overexpression of MIAT in tumor tissues has been reported in several cancer types." (PMID 31372094, 2019). "Recent studies found that MIAT was involved in cancer progression via sponging miRNAs." (PMID 31372094, 2019). "Recently, MIAT was found to be an oncogenic lncRNA in various cancers." (PMID 29487526, 2018). "We found that MIAT expression was higher in cancer cell lines than in MCF-10A." (PMID 29100300, 2017).
cancer (continued). "In cancer research, lncRNA MIAT is selectively upregulated in neuroendocrine prostate cancer and might interact with Polycomb genes." (PMID 29100300, 2017). "We note that no cancer-associated copy number alteration or SNP has been reported at MIAT locus on chromosome 22q12.1." (PMID 27527866, 2016). "MIAT serves as a T cell marker in LncCE, which is identified as a CE lncRNA in 20 adult cancer datasets, and it is primarily expressed in tumor and T cells, indicating that MIAT may be involved in the immune escape process of cancer." (PMID 40833782, 2025). "Notably, MEG3, MIAT, Malat1, SNHG20, SNHG12, Ftx, Pvt1, Mir9-3hg expression in cancer immune cells was associated with an immunosuppressive phenotype, while H19, SNHG6, Trp53cor1, MiR17hg and MiR142hg were linked to a pro-inflammatory phenotype in cancer." (PMID 40527978, 2025). "Functional studies and gene expression determination confirm that MIAT knockdown not only affects short- and long-term survival and the apoptosis of leukemic cells but also plays a pivotal role in the alteration of key genes involved in cancer, including c-MYC and HIF-1A." (PMID 37624039, 2023). "Hence, MIAT may provide a therapeutic target for several cancers, including prostate and non-small-cell lung cancers." (PMID 30967527, 2019). "LncRNAs, such as LUCAT1, KCNMB2-AS1, CASC15, MIAT, PTOV1-AS2, LINC00680, and RNF217-AS1 were reported to be up-regulated in ESCC and other malignant tumors, validating our RNA-sequencing results." (PMID 35255921, 2022). "The RT-qPCR assay showed upregulation of MIAT and STC1 while downregulation of hsa-miR-532-3p expression in cancer." (PMID 35607443, 2022). "Splendid positive correlations were found between the MIAT and EZH2 expression in types of cancer in TCGA data." (PMID 34811354, 2021). "In the functional assays, overexpression of LASP1 recovered MIAT silencing induced cell proliferation, invasion and cycle inhibition, suggested that MIAT relied on regulation of LASP1 to regulate PTV cancer progression." (PMID 31372094, 2019). "Knockdown of MIAT also enhanced gefitinib cytotoxicity through inactivating PI3K/AKT signaling, an important pathway to promote cancer cell proliferation." (PMID 29487526, 2018). "LncRNAs such as MIAT, SNHH16, LUCAT1, OIP-AS1, MALAT-1, GAS5, and H19, which regulate functions that might disrupt different steps of the cancer–immunity cycle, have been found in EVs." (PMID 40429961, 2025). "MIAT upregulation in the tumor tissues was associated with an advanced stage (stages III, IV, n = 24, p = 0.001) but not early stage cancer (stages I and II, n = 36, p = 0.09)." (PMID 29228680, 2017). "Recent evidence has displayed that MIAT is upregulated in lymphoid cell lines with mature B cell phenotypes and that MIAT created a regulatory mechanism with the protein OCT4 (octamer-binding transcription factor 4), allowing apoptosis and cell death evasion, ultimately promoting cancer progression." (PMID 37624039, 2023). "Specially, MIAT and MIR155HG could be detected in blood of cancer patients." (PMID 37770497, 2023). "Interestingly, our study also revealed hub genes (MEG3, MIAT, IRF1, ADAMTS9-AS2, TP63, NOD2, NOD1, NLRP3, MAGI2-AS3, and PVT1, respectively) within the pyroptosis-related ceRNA network, some of which have been well-studied in the field of cancer biology." (PMID 37511974, 2023). "In addition, our data also found that miR-132 inhibitor could reverse the anti-cancer effects of MIAT knockdown on cell growth, metastasis and negative role of si-MIAT on cell apoptosis in CRC cells." (PMID 29686537, 2018).
tumor (53 papers, 2017 to 2026). "Bioinformatic analyses further indicated that the rs4274 A allele is associated with increased MIAT expression, and higher MIAT levels correlated with higher tumor grade." (PMID 41938500, 2026). "In conclusion, the MIAT rs4274 A allele is linked to poorer tumor differentiation, particularly among betel-quid chewers and smokers, and elevated MIAT expression supports its potential as a biomarker of tumor aggressiveness." (PMID 41938500, 2026). "We found, for the first time, that the MIAT rs1061540 variant was associated with the risk of malignant epithelial OC and the tumor grade." (PMID 38390896, 2024). "We found that MIAT is upregulated in NBL tumor tissues and cell lines, and MIAT levels are associated with NBL and its NMYC status." (PMID 33806217, 2021). "Here we sought to clarify this possibility and elucidate the mechanism underlying the anti-tumor activity of MIAT." (PMID 32549789, 2020). "A loss-of-function assay demonstrated that MIAT silencing impaired cell proliferation, migration, and invasion in vitro and inhibited tumor formation in vivo." (PMID 29228680, 2017). "Low MIAT abundance significantly associated with tumor progression, stage and metastasis as well." (PMID 32549789, 2020). "MIAT silencing can lead to tumor cell growth arrest, thereby increasing the sensitivity of BRCA treatment." (PMID 39911848, 2025). "It downregulated several potential oncogenes (e.g., AEBP1, MIAT) and genes linked to GBM proliferation and migration (e.g., SOCS2, HCP5) while modulating Wnt signaling and up-regulating tumor suppressor genes (e.g., SPRY4, BEX2)." (PMID 39874307, 2025). "Further in vivo experiments showed that the suppression of MIAT repressed growth of tumour cells in mice." (PMID 40863727, 2025). "The knocking down of MIAT has resulted in decreased cell viability, migration and invasion, as well as cell cycle arrest at the G0/G1 phase, suggesting its role in tumour progression." (PMID 40863727, 2025). "MIAT acts as a tumor-promoting gene and exerts essential roles in the cell cycle, immune infiltration, and in responding to estrogen in BC." (PMID 37511974, 2023). "The high expression of MIAT is related to the clinicopathological characteristics of tumor patients." (PMID 36230580, 2022). "Recently, it has been shown that MIAT is widely overexpressed in many tumors, and the expression level of MIAT is positively correlated with lymph node metastasis, tumor stage, and prognosis of tumor patients." (PMID 35607443, 2022). "PCR assays showed that the MIAT expression levels were downregulated in tumor tissues collected from the sh-MIAT group compared with the controls, and the relative downstream components including EZH2, p16, p15, and p27 decreased significantly." (PMID 34811354, 2021). "We obtained four sensitive tumor samples and four resistant tumor samples and analyzed the expression levels of lncRNA MIAT, HMGB1, and IL6." (PMID 34094941, 2021). "In the present study, MIAT was confirmed to be crucial in the growth of tumor cells, invasion, and promotion of apoptosis of tumor cells." (PMID 34108986, 2021). "In the previous study, LINC00443 was reported as a tumor suppressor, which was associated with a better prognosis of KIRC, while MIAT was associated with worse prognosis." (PMID 32694941, 2020). "Reduced MIAT expression remarkably restrained proliferation and invasion in vitro and inhibited tumor growth in vivo." (PMID 32274858, 2020). "Using RNA-seq method, we discovered that MIAT was one of the most significantly elevated lncRNAs in PTC tumor tissues compared with matched normal tissues." (PMID 31372094, 2019).
tumor (continued). "Small interfering RNA specific for MIAT (si-MIAT) and lentivector for si-MIAT was performed to down-regulate MIAT expression in GC cells and in animal tumor model, respectively." (PMID 29540201, 2018). "The result showed that DDX5 expression was significantly decreased in tumor tissues down-regulating MIAT." (PMID 29540201, 2018). "Of those miRNAs, we found that 7 miRNAs (miR-503, miR-133, miR-139, miR-204, miR-338, miR-128 and miR-141), which acted as tumor suppressors in GC, were likely down-stream target of MIAT." (PMID 29540201, 2018). "Subsequent analyses demonstrated that the expressions of PVT1 and CYTOR were up-regulated, while HAR1A and MIAT were down-regulated in diffuse glioma samples compared to non-tumor tissues." (PMID 29108264, 2017). "In conclusion, our results clarified that MIAT was upregulated in NSCLC tumor tissues and was correlated with tumor advanced stage." (PMID 29228680, 2017). "In this study, we observed that MIAT expression was upregulated in NSCLC, and its overexpression was associated with advanced tumor stage." (PMID 29228680, 2017). "We found that MIAT knockdown significantly reduced the tumor volume of MDA-MB-231 cells compared with control group." (PMID 29100300, 2017). "Our results showed that the relative expression levels of CYTOR and PVT1 were up-regulated, while HAR1A and MIAT were significantly down-regulated in diffuse glioma specimens compared to non-tumor tissues (all P <0.001)." (PMID 29108264, 2017). "This implies that MIAT is involved in the tumor’s immune microenvironment and drug response." (PMID 41154428, 2025). "Numerous tumor associated lincRNAs were identified, such as PVT1, HIF1A-AS1 and MIAT." (PMID 36071454, 2022). "To determine whether MIAT is also expressed in tumor tissue and not only in cell lines, we analyzed the MIAT RNA expression using the RNA-ISH method in a total of 21 formalin-fixed paraffin-embedded (FFPE) tissues." (PMID 33806217, 2021). "The MIAT expression was also measured in HDFn as representative of non-tumor cells using qRT-PCR." (PMID 33806217, 2021). "Xenograft tumor progression was significantly inhibited by forced overexpression of MIAT, with the average weight of tumor mass was 1.38 ± 0.38 g in wild-type recipients versus 0.62 ± 0.19 g in MIAT-proficient group." (PMID 32549789, 2020). "The expression status of MIAT-miR-150-5p-CDKN1B signal axis was further characterized in xenograft tumor at both transcriptional and translational levels, which consolidated our in vitro observations and supported the physiological role of MIAT as ceRNA for miR-150-5p." (PMID 32549789, 2020). "Furthermore, in a large cohort (TCGA, cell 2014), expression of MIAT was positively correlated with LASP1 levels in tumor from 486 patients with PTC (r = 0.292, p < 0.0001)." (PMID 31372094, 2019). "We speculated that the higher the expression of MIAT, the more sensitive it may be to tumor immunotherapy." (PMID 31649871, 2019). "Furthermore, MIAT knockdown significantly inhibited tumor growth in vivo and decreased the expression of the proliferation marker Ki67." (PMID 30967527, 2019). "MIAT expression was also found to be up-regulated in ER, PR, and Her2 positive tumor tissues." (PMID 29914974, 2018). "The down-regulation of MIAT in tumor lysates was also confirmed." (PMID 29540201, 2018). "Furthermore, our data demonstrated that MIAT knockdown inhibited tumor growth in nude mice xenografts." (PMID 29540201, 2018). "Besides, the expression of miR-141 was significantly increased in tumor tissues down-regulating MIAT." (PMID 29540201, 2018). "Compared with NC control group, knockdown of lncRNA MIAT significantly inhibited tumor growth." (PMID 29487526, 2018). "And the tumor formation was later in MIAT knockdown group than the control group." (PMID 29100300, 2017). "And downregulation of MIAT decreased tumor growth and delayed tumor formation in vivo." (PMID 29100300, 2017).